PRDX2 (peroxiredoxin 2)
Diseases named in the same sentence as PRDX2 in open-access papers (continued):
Sharing a sentence is not in itself a finding about the gene and the disease.
liver cancer (2 papers, 2025). An epithelial or non-epithelial malignant neoplasm that arises from the liver. "Peroxiredoxin 2 was identified as a candidate target for the prevention of liver cancer in patients with chronic liver disease induced by metabolic disorders." (PMID 40932790, 2025). "Because AMPK function is often impaired in metabolic liver disease and liver cancer, we hypothesized that AMPK activity is impaired in DEN/CDA-HFD and that Prdx2 KO may restore AMPK functions." (PMID 40932790, 2025).
liver disease (2 papers, 2020 to 2025). "PRDX2 is associated with liver disease progression and HCC risk." (PMID 40932790, 2025). "Considering the importance of oxidative stress in liver disease progression, we explored the role of PRDX2 in hepatocarcinogenesis." (PMID 40932790, 2025). "PRDX2 KO reversed the poor-prognosis cPLS associated with HCC risk, indicating a functional role of PRDX2 in the cell circuits driving liver disease progression to cancer." (PMID 40932790, 2025). "Alteration of PRDX2 expression in liver disease and HCC may be a bystander effect due to progressive increase in oxidative stress that exacerbates cell damage and transformation." (PMID 40932790, 2025). "Prdx2 KO had no significant impact on other Prdxs’ expression, indicating that the effect on liver disease is not due to compensatory effect." (PMID 40932790, 2025).
Miscarriage (2 papers, 2021 to 2023). A pregnancy that ends at a stage in which the fetus is incapable of surviving on its own, defined as the spontaneous loss of a fetus before the 22th week of pregnancy. "Furthermore, PRM technology was employed to validate three proteins—CD45, PSG1, and Prdx-2—which were found to be closely associated with miscarriage." (PMID 37587463, 2023). "More recently, another study found that peroxiredoxin 2 downregulation plays a role in recurrent miscarriage through regulation of trophoblast proliferation and apoptosis via effects on ROS metabolism." (PMID 33618676, 2021).
multiple sclerosis (2 papers, 2017 to 2019). A progressive autoimmune disorder affecting the central nervous system resulting in demyelination. "On the other hand, PRDX2 is a peroxidase which has been considered a biomarker in inflammatory processes such as multiple sclerosis." (PMID 30648003, 2019).
oral cancer (2 papers, 2018 to 2020). "As expected, both arecoline treatment (low concentration) and HPV16 E6/E7 could induce PRDX2 overexpression in oral cell lines including oral cancer (ORL-48T and ORL-136T) and immortalized tongue keratinocyte (HTK1T-KTD4) cell lines." (PMID 33332365, 2020).
osteoporosis (2 papers, 2020 to 2022). A condition of reduced bone mass, with decreased cortical thickness and a decrease in the number and size of the trabeculae of cancellous bone (but normal chemical composition), resulting in increased fracture incidence. "It has been demonstrated that circulating levels of catalase, superoxide dismutase 2 (SOD 2) and peroxiredoxin 2 (PRX2) are lower in postmenopausal women with osteoporosis than health controls." (PMID 35387349, 2022).
squamous cervical cancer (2 papers, 2017 to 2019). "High levels of thioredoxin 1, peroxiredoxin 1 and peroxiredoxin 2 were associated with a poor chemotherapy response in cervical squamous cancer patients." (PMID 31470801, 2019). "Thioredoxin 1, peroxiredoxin 1 and peroxiredoxin 2 are frequently over-expressed in cervical squamous cancer." (PMID 31470801, 2019). "Then, correlation between the expression of thioredoxin 1, peroxiredoxin 1, peroxiredoxin 2 and responses to cisplatin-based neoadjuvant chemotherapy was analyzed in 35 paired tumor samples (pre- and post-chemotherapy) from bulky cervical squamous cancer patients by immunohistochemistry." (PMID 31470801, 2019). "The expression of thioredoxin 1, peroxiredoxin 1 and peroxiredoxin 2 was much higher in cervical squamous cancer tissues compared with paired adjacent non-cancerous tissues by western-blotting and immunohistochemistry." (PMID 31470801, 2019). "Initially, the expression of thioredoxin 1, peroxiredoxin 1 and peroxiredoxin 2 protein was analyzed in 13 human cervical squamous cancer tissues and their paired adjacent non-cancerous tissues by western-blotting and immunohistochemistry." (PMID 31470801, 2019).
tendinopathy (2 papers, 2022 to 2023). "Other candidate tendinopathy genes associated with breed group differences in DSLD risk identified in this study include PRDX2 and GREM2." (PMID 35866615, 2022). "Our study suggested that FOXO1 affected tendinopathy progression by regulating PRDX2 transcriptional activity." (PMID 37223090, 2023). "All these results confirmed that diseased cells with low PRDX2 expression maintained a worse cellular state, hindering tendinopathy recovery." (PMID 37223090, 2023). "In summary, PRDX2 was to blame for the deterioration of diseased cells (TDSC-7) in tendinopathy." (PMID 37223090, 2023). "We carried out PCR to test the hypothesis suggesting that the FOXO1 motif is related to PRDX2 expression in tendinopathy." (PMID 37223090, 2023). "PRDX2, a member of the peroxiredoxin family of antioxidant enzymes, has been identified as a signaling in diseased cells (TDSC-7) in tendinopathy." (PMID 37223090, 2023). "Since only PRDX2 was expressed less in tendinopathy than in control normal tendon tissue in both the microarray cohorts and that it was expressed in almost all TDSCs, except the TDSC-7 cluster cells, we hypothesized that PRDX2 is a potential specificity marker and an ideal target for diseased cells." (PMID 37223090, 2023).
varicocele (2 papers, 2020). A condition characterized by the dilated tortuous veins of the spermatic cord with a marked left-sided predominance. "Proteins associated with oxidative stress (PRDX2), DNA fragmentation (fatty acid synthase; FASN) and the inflammatory response (FN1) were also overexpressed in the bilateral varicocele group, indicating an increased inflammation and oxidative stress in this group, compared to unilateral varicocele." (PMID 32987677, 2020).
Alzheimer disease (1 paper, 2021). A progressive, neurodegenerative disease characterized by loss of function and death of nerve cells in several areas of the brain leading to loss of cognitive function such as memory and language. "According to the Reactome database, PRDX2 is related to pathways involved in ROS detoxification, Alzheimer's disease, and neurodegenerative diseases." (PMID 33656056, 2021).
aneurysm (1 paper, 2020). Bulging or ballooning in an area of an artery secondary to arterial wall weakening. "In a study comparing the proteomic composition of aneurysmal aortas in patients with nonruptured aneurysms and those with ruptured aneurysms, higher levels of PRDX2 were revealed in patients with ruptured AAAs than in those with nonruptured AAAs27." (PMID 32929220, 2020).
aneurysmal diseases (1 paper, 2020). "Using ultrasound imaging and histological analysis, we demonstrated that the loss of PRDX2 induced an increase in AAA incidence along with aortic dilatation and the structural warping of aortas following an increase in the infiltration of inflammatory cells into lesions and MMP activation." (PMID 32929220, 2020). "In addition to increased aortic dilatation, we identified an increase in turbulent blood flow in the suprarenal regions of the abdominal aorta in Prdx2−/− mice infused with Ang II compared with that in controls using color and pulsed wave Doppler." (PMID 32929220, 2020). "Although there is a need to examine the potential therapeutic role of PRDX2 in AAA, our data support the importance of PRDX2 in the development of aneurysmal diseases." (PMID 32929220, 2020).
Anxiety (1 paper, 2024). Intense feelings of nervousness, tension, or panic often arise in response to interpersonal stresses. "Research on hypertensive rats showed that telmisartan reduced oxidative stress and improved peroxiredoxin-2 (Prdx2) expression, further supporting its potential to manage anxiety via antioxidant pathways." (PMID 39429389, 2024).
Apnea (1 paper, 2020). Lack of breathing with no movement of the respiratory muscles and no exchange of air in the lungs. "The redox–oligomeric states of GAPDH and PRDX2 involving overoxidation by sulfinic/sulfonic acids were differentially modulated in OSA RBC probably due to the nocturnal apnea-induced intermittent hypoxia that was chronically experienced by these patients." (PMID 33256145, 2020).
Arthritis (1 paper, 2025). Inflammation of a joint. "This study elucidates CAP's antiarthritic mechanism via PRDX2 targeting, revealing therapeutic potential for arthritis." (PMID 40443720, 2025).
attic cholesteatoma (1 paper, 2013). "In this study, the expression of HSP27, PRDX2, GRP75, GRP78 and GRP94 was found upregulated in acquired attic cholesteatoma by comparing 2-DE maps of cholesteatoma tissues with those of the retroauricular skin of the patients." (PMID 23852020, 2013).
autism spectrum disorder (1 paper, 2023). A spectrum of developmental disorders that includes autism, and Asperger syndrome. "The level of membrane-bound Prdx2 was not changed in erythrocytes of patients with autism spectrum disorder, but the blood plasma level of Prdx2 was increased." (PMID 37237878, 2023).
bladder tumors (1 paper, 2022). "Materials and Methods: PRDX1 and PRDX2 expression levels were examined in 119 bladder tumor specimens by immunohistochemistry and in 150 urine samples (case: 100; healthy controls: 50) using ELISA and their association with recurrence and survival of patients was evaluated." (PMID 35812179, 2022).
Bloom syndrome (1 paper, 2017). Bloom syndrome (BSyn) is a rare chromosomal breakage syndrome characterized by a marked genetic instability associated with pre- and postnatal growth retardation, facial sun-sensitive telangiectatic erythema, increased susceptibility to infections, and predisposition to cancer. "Interestingly, T cell-related genes (D.3) were downregulated (Bloom syndrome, E2F transcription factor 1 and peroxiredoxin 2) in the RAG1−/− compared to the WT." (PMID 28596766, 2017).
brain hemorrhage (1 paper, 2022). "However, the precise mechanism for the action of Prdx2 in the disorders that occur during brain hemorrhage needs to be clarified in the future." (PMID 35052630, 2022). "Although the precise mechanism for the role of extracellular Prdx2 in the pathogenesis of brain hemorrhage has not been elucidated, the activation of TLR4 by extracellular Prdx1 has also been reported to be involved in the neuroinflammation that occurs during intracerebral hemorrhagic injury." (PMID 35052630, 2022).
brain tumors (1 paper, 2023). "To gain deeper insight into the expression pattern of PRDX1 and PRDX2 in brain tumors, we first examined the level of each of these isoforms in NT and GBM tissues." (PMID 37566013, 2023).
cardiomyopathy (1 paper, 2018). A disease of the heart muscle or myocardium proper. "Our data suggest that PRDX2, a redox regulating molecule, is involved in early-phase left ventricular impairment in hamsters with cardiomyopathy." (PMID 29438398, 2018). "Therefore, our data suggest that PRDX2 is a promising novel marker of early-phase LV impairment in cardiomyopathy." (PMID 29438398, 2018). "Thus, we believe that the observation of present study suggests that PRDX2 is a promising novel marker of early-phase LV impairment in cardiomyopathy." (PMID 29438398, 2018).
choledocholithiasis (1 paper, 2023). Presence or formation of gallstones in the common bile duct. "Similarly, in serum samples, PRDX2 level was notably elevated in HCC causes compared to choledocholithiasis." (PMID 38188679, 2023). "Our results revealed a significantly higher expression of PRDX2 in the bile of HCC patients compared to choledocholithiasis patients." (PMID 38188679, 2023). "In bile, the expression level of PRDX2 in HCC patients was markedly higher than that in choledocholithiasis patients (median level 9,395 vs. 4,858 ng/ml, p = 0.000)." (PMID 38188679, 2023). "In our study, we initially confirmed a higher level of PRDX2 in the bile of HCC patients compared to those with choledocholithiasis by 2-DE, LC-MS, and ELISA." (PMID 38188679, 2023). "Similarly, the level of PRDX2 in serum of HCC patients was notably higher than that in choledocholithiasis patients (median level 5,780 vs. 3,743 ng/ml, p = 0.000)." (PMID 38188679, 2023).
cholesteatoma (1 paper, 2013). A pathologic process characterized by the proliferation of keratinizing squamous epithelium resulting in the accumulation of keratin and cells in the middle ear and/or mastoid. "In the current study, increased expression of Peroxiredoxin2 (PRDX2) was shown by proteomic analysis and Western blot in cholesteatoma." (PMID 23852020, 2013). "The results of this study suggested that phosphorylated HSP27 is the end expression of two potential signal-transduction pathways, and together with PRDX2, they are very likely involved in the proliferation of keratinocytes in cholesteatoma." (PMID 23852020, 2013). "Taken together, in the current study, HSP27 and PRDX2 were enhanced, and phosphorylation of HSP27 at Ser-82 was identified in acquired attic cholesteatoma tissue." (PMID 23852020, 2013). "The side-by-side comparison of HSP27, PRDX2, GRP75, GRP78 and GRP94 for each individual patient shows that these proteins are increased in cholesteatoma compared with those in retroauricular skin." (PMID 23852020, 2013). "Expression of HSP27, PRDX2, GRP78 and GRP94 in the tissues of cholesteatoma and retroauricular skin assessed by RT-PCR and Western blotting analysis is coherent with the 2-DE results." (PMID 23852020, 2013). "Changes of HSP27, PRDX2, GRP75, GRP78 and GRP94 in the tissues of cholesteatoma and the retroauricular skin of six patients were further validated by Western blotting analysis." (PMID 23852020, 2013).
chronic myeloid leukemia (1 paper, 2017). "In the chronic myeloid leukemia model (K562Dox) the following 4 DEPs were found to be involved in the GSH metabolism pathway (G6PD, PRDX2, IDH1 and 6PGD), 3 DEPs in the PPP pathway (G6PD, ALDOC and 6PGD) and 2 DEPs in the glycolysis pathway (ALDOC and PKM2)." (PMID 28303926, 2017).
Cirrhosis (1 paper, 2025). A chronic disorder of the liver in which liver tissue becomes scarred and is partially replaced by regenerative nodules and fibrotic tissue resulting in loss of liver function. "PRDX2 was identified as a key regulatory gene in central module 8, coregulated with the tumor suppressor HINT1, which is the only module associated with increased HCC risk independently from cirrhosis." (PMID 40932790, 2025).
colitis (1 paper, 2019). Inflammation of the colon. "Peroxiredoxin 2 (PRDX2) was transiently increased during mild colitis development, whereas transferrin (TF) was only increased later in severe colitis mice." (PMID 30774653, 2019).
colorectal adenocarcinoma (1 paper, 2020). The most common type of colorectal carcinoma. "To confirm our results, we investigated links between PRDX2 and cell-cycle and autophagy genes in CRC patients using the CGDSR-R and mRNA (microarray) data from an independent TCGA colorectal adenocarcinoma cohort consisting of 222 samples." (PMID 32692719, 2020).
colorectal adenoma (1 paper, 2017). An adenoma that arises from the colon or rectum. "In agreement with the result of Western blotting assay, immunohistochemical analysis also showed PRDX2 over-expression in all six tumors in comparison with the noncancerous tissues adjacent to colorectal adenomas." (PMID 28125800, 2017).
colorectal tumor (1 paper, 2021). "Notably, compared to the other PRDXs, PRDX2 was identified in our previous study as the most highly expressed upregulated protein in colorectal tumor tissue." (PMID 33819194, 2021).
COVID-19 (1 paper, 2024). A disease caused by infection with severe acute respiratory syndrome coronavirus 2. "The COVID-19 convalescents had significantly elevated immunoglobulins, Orosomucoid 2 (ORM2), peroxiredoxin-2 (PRDX2), hemoglobin subunits (HBD, HBB and HBA1), as well as proteins involved in cholesterol transport such as cholesteryl ester transfer protein (CETP) and apolipoprotein A1 (APOA1)." (PMID 38396092, 2024). "In comparison, clusters D and E had proteins with higher levels in COVID-19 convalescents, e.g. immunoglobulins playing a role in antigen recognition (e.g. IGKV1-27, IGKV1-39, IGHV1-46, IGLV3-1, and PRDX2), hemoglobin subunits (e.g. HBB, HBA1, and HBD), and carbonic anhydrase (CA1)." (PMID 38396092, 2024).
edema (1 paper, 2023). An abnormal accumulation of fluid beneath the skin, or in one or more cavities of the body. "The oozing blood leads to initial brain damage through physical destruction and the mass effect, as well as secondary brain damage, such as cerebral edema and delayed cerebral infarction, by releasing potentially neurotoxic and proinflammatory factors (e.g., hemoglobin, iron, and peroxiredoxin-2)." (PMID 37759833, 2023).
endometrial cancer (1 paper, 2022). Primary or metastatic malignant neoplasm involving the endometrium (mucous membrane that lines the endometrial cavity). "The obtained results indicate the overexpression of PRDX2 and PKD2 in endometrial cancer, regardless of its grade, which is consistent with the analysis at the mRNA level." (PMID 36555458, 2022).
endometritis (1 paper, 2024). An acute or chronic, usually bacterial infectious process affecting the endometrium. "The following genes were assessed for their expression levels using real-time PCR in both the normal and endometritis-affected buffaloes: immune (TLR4, IL-8, IL-17, NFKB, SLCA11A1, and NCF4) and antioxidant (SOD, CAT, NDUFS6, Nrf2, Keap1, PRDX2, HMOX1, OXSR1, ST1P1, and SERP1)." (PMID 39195794, 2024).
enterocolitis (1 paper, 2025). An inflammatory process affecting the small intestine and colon. "Moreover, we detected the decreased levels of PRDX2, HSPA1B, and catalase, suggesting a diminished antioxidative capacity in NEC, which was consistent with previous studies on necrotizing colitis or enterocolitis." (PMID 39562369, 2025).
erectile dysfunction (1 paper, 2023). Persistent or recurrent inability to achieve or to maintain an erection during sexual activity. "Our results further demonstrated changes in the expression of key proteins (GPX4 and ACSL4) in the ferroptosis pathway, whereas PRDX2-ADSCs ameliorated BCNI-induced erectile dysfunction and ferroptosis of the corpus cavernosum in NED rats." (PMID 36819780, 2023). "In conclusion, overexpression of PRDX2 in ADSCs enhanced the therapeutic effect in a rat model of neurogenic erectile dysfunction by inhibiting ferroptosis via regulation of the GPX4/ACSL4 axis." (PMID 36819780, 2023).
experimental autoimmune encephalomyelitis (1 paper, 2017). An autoimmune demyelinating disease of the central nervous system that is produced experimentally in animals by the injection of homogenized brain or spinal cord in Freund's adjuvant. "Further studies will have to analyze the effects of PRDX2 loss under pathophysiological conditions such as experimental autoimmune encephalomyelitis, an animal model for MS." (PMID 28375164, 2017).
fibrosis (1 paper, 2017). the formation of excess fibrous connective tissue in an organ or tissue in a reparative or reactive process. "Likewise, the anti-oxidant peroxiredoxin-2 was also found to be down-regulated in the fibrosis model samples." (PMID 28662027, 2017).
G6PD deficiency (1 paper, 2023). An X-linked genetic condition caused by alterations in the gene G6PD that result in moderately to severely decreased activity levels of the enzyme glucose-6-phosphate dehydrogenase. "The syndrome of G6PD deficiency limits NADPH production via the pentose phosphate pathway and prevents efficient recycling of Prdx2 in erythrocytes under oxidative stress." (PMID 37237878, 2023).